TNF (tumor necrosis factor)
Diseases named in the same sentence as TNF in open-access papers (continued):
Sharing a sentence is not in itself a finding about the gene and the disease.
lupus (continued). "Functional enrichment analyses identified several metabolic pathways (i.e., systemic lupus erythematosus, PI3K-Akt, TNF, JAK-STAT, IL-17, MAPK, Rap1 and signaling pathways) enriched with upregulated and downregulated genes when combined JQ1 and GSK2801 treatment was administered." (PMID 35672711, 2022). "In our study, the levels of TNF-α, IL-17, and MCP-1were gradually upregulated with time, demonstrating that these proteins may be responsible for lupus activity." (PMID 35804318, 2022). "Furthermore, 6-gingerol suppressed the production of proinflammatory cytokines, such as TNF-α and IFN-γ, similar to PDE4 inhibitors, therefore exerting an overall antiinflammatory effect in TLR7 agonist–induced lupus." (PMID 33373329, 2021). "Secondary MN occurs in association with other diseases such as systemic lupus erythematosus (SLE), infections and malignancies, or exposure to toxins as wells as certain medications such as non-steroidal anti-inflammatory drugs, penicillamine, probenecid, and TNF alpha blockers." (PMID 33825066, 2021). "BM-MSCs from a lupus mouse model have shown proinflammatory rather than inhibitory phenotype when stimulated by IL-1 and TNF-α." (PMID 34067727, 2021). "This case control study used 46 KOA patients (pKOA, n = 30; sKOA, n = 16), and 60 age, gender matched controls (normal healthy, n = 30; systemic lupus erythematosus [SLE] disease controls, n = 30) where serum was assayed for cytokines (TNF-α, IL-1β, IL-6, IL-10) and nitric oxide derivatives (NOx)." (PMID 34543351, 2021). "Tumor necrosis factor (TNF)-like weak inducer of apoptosis (TWEAK) and its cognate receptor Fn14 have been shown to play an important role in neurocognitive dysfunction in murine lupus." (PMID 33578738, 2021). "Both lupus patients and female NZBWF1 mice express elevated levels of several pro-inflammatory cytokines including IFNα, TNFα, IFNγ that may act to differentiate immunosuppressive MDSCs into proinflammatory MDSCs." (PMID 34220829, 2021). "Serum proinflammatory cytokines, including IL-17a, IFN-γ, IL-6, TNF, and IL-2, were significantly increased, while the anti-inflammatory cytokine IL-10 was significantly decreased in sodium chloride-pretreated BMDC-ALD-DNA-induced lupus mice." (PMID 32296043, 2020). "Interestingly, work in a lupus model demonstrates that overexpression of biglycan, a DAMP that is related to Dcn, induces similar levels of TNFα in spelenic tissues as were observed in our pSS mice." (PMID 31993047, 2019). "In addition, we found the UC-MSCs induced CD1c+DCs in the lupus patients exerted tolerogenic properties by decreasing expression of CD80, CD83, CD86 and HLA-DR, decreasing production of TNFα and keeping production of IL-10." (PMID 31175312, 2019). "In the known mouse models of spontaneous lupus, MRL/lpr mice develop similar pathological reactions to that of SLE patients, like renal damage as well as abnormal horizontal expression of cytokines IL-2, IL-4, IL-17, and TNF-α." (PMID 31781262, 2019). "By contrast, lupus IgG enhanced the serum TNF-α level in normal mice, but not in macrophage-depleted mice." (PMID 29988500, 2018). "Drug-induced lupus refers to an autoimmune disorder that resembles SLE and is actually an idiosyncratic adverse effect of certain medications, particularly hydralazine, procainamide, isoniazid, minocycline, diltiazem and TNF inhibitors." (PMID 29896474, 2018). "All these findings indicated that the levels of TNF-α and IFN-α (and its signatures) might influence the development of lupus-like autoantibody production following treatment with TNFi in humans." (PMID 27643491, 2016). "African American women also had the highest level of TNF-α when compared to nonlupus and lupus European American women and men in general." (PMID 26583155, 2015).
lupus (continued). "Other previously noted usage patterns include the use of the anti-seizure medications such as pregabalin and lamotrigine for migraines, and the use of immuno-modulators such as etanercept and adalimumab, two Tumor Necrosis Factor (TNF) inhibitors, for systemic lupus erythematosus (SLE)." (PMID 24586689, 2014). "In order to induce renal damage, researchers have suggested that TNF-α interacts with pathologic mediators present either locally or in the circulation that are not synthesized in pre-disease lupus-prone mice." (PMID 24171032, 2013). "Consistent with above results in vitro, MBL treatment could suppress the pro-inflammatory cytokine TNF-α, MCP-1 and IL-6 while increase the expression of IL-10 in the renal macrophages and in serum of lupus mice." (PMID 23626823, 2013). "The protein product of IRF5, a lupus susceptibility gene, acts as a transcription factor to mediate TLR induction of proinflammatory cytokines IL-6, IL-12, TNFα and, to some extent, IFN-α, independent of NF-κB." (PMID 23557436, 2013). "Elevated TNFα has been reported in the sera of some patients with systemic lupus erythematosus, DLE and SCLE, but not in the sera of patients with DM." (PMID 22217359, 2012). "In the case of anti-TNFα DILE, if the clinical presentation of drug-induced lupus is mild and well tolerated, TNFα inhibitors do not need to be discontinued." (PMID 22937775, 2012). "TNFα has been reported to be elevated in sera of some patients with systemic lupus erythematosus (SLE), DLE and SCLE, but not in that of patients with DM." (PMID 22217359, 2012). "Taken together, these data suggest that the abnormal secretion of TNF-α by lupus monocytes is a process independent of apoptotic cell engulfment." (PMID 21423726, 2011). "Range of TNF-α and TGF-β secretion by lupus monocytes upon activation with apoptotic cells." (PMID 21423726, 2011). "Together, common characteristics of lupus appear to be upregulation of members of the IL-1 family such as IL-1α and IL-1β and IL1R2, of the TNF/death receptor family such as TNF receptor II (TNFRSF1B), TRAIL (TNFSF10), and its decoy receptors, and a gene signature of IFN-α/β-regulated genes." (PMID 19884985, 2009). "Our data revealed amelioration of BTN3A1‐induced lupus‐like changes, such as improved degree of renal injuries and reduced percentage of CD3+, CD8+ T cells, Th1, Th2, Th17 cells, upregulated percentage of Treg cells, and lower expression of IL‐4, IL‐6, IL‐10, IL‐17A, IFN‐γ, TNF‐α, and dsDNA." (PMID 40959207, 2025). "Thus, TNF blockade may lead to sustained IFN-α secretion, which could contribute to ANA induction and, in some cases, lupus-like manifestations." (PMID 40095466, 2025). "Studies have demonstrated the effectiveness of anti-TNF-α therapies in treating connective tissue diseases (CTD), particularly SLE and cutaneous lupus erythematosus (CLE)." (PMID 40791585, 2025). "In parallel, an experimental treatment of 6-gingerol on mice induced with lupus showed reductions in the levels of the pro-inflammatory TNF-α and IFN-γ isotypes, pointing to its good effects on SLE’s usual general inflammation aspects." (PMID 40534849, 2025). "The identified TNF transcriptional enrichment in lupus stems from cytokine signaling through classical NF-κB–dependent pathways but may not be directly mediated by TNF-α itself." (PMID 39688922, 2024). "The occurrence of systemic lupus erythematosus (SLE) is closely related to IFN: the combination of IFN-α and TNF can increase the chromatin accessibility of tolerance genes (such as IL6), leading to the appearance of tolerant monocytes." (PMID 38586584, 2024). "Additionally, GSEA also revealed an association with immunologic signature terms, including “GSE10325 CD4 T-cell vs lupus CD4 T-cell up”, “GSE19198 1 h vs 24 h IL21 treated T-cell up”, “GSE15930 naïve vs 24 h in vitro stim CD8 T-cell down”, “GSE18893 tconv vs treg 24 h TNF stim up”, etc.." (PMID 37161020, 2023).
lupus (continued). "Interestingly, we found similar populations of IL-10 producing cells from scRNA-seq of lupus-prone mice as these markers were expressed by the Phagocytic PB-PC and TIM-1 B Cell populations from pre-disease mice and the TACI/TNF B Cell and TIM-1 B Cell populations from active-disease mice." (PMID 38155972, 2023). "Systemic Lupus Erythematosus (SLE) features excessive ROS production shaped by genetic factors like IFN-α, IL-1, IL-6, and TNF-α, highlighting the genetic facets of immune dysregulation." (PMID 38248493, 2023). "Moreover, there was increased expression of TNFα and pp65 in the cerebral cortex and hippocampus, long immobility period of MRL/lpr mice, and low expression of pIκBα in the hippocampus and total and center track lengths of lupus mice." (PMID 38164134, 2023). "Similarly, FcγRIIb−/− lupus mice treated with etanercept upregulated cancellous bone volume and cortical thickness and downregulated expression of osteoblast marker genes (OSX, Collagen type I α 1) and serum levels of TNFα, IFNγ, IL-6, and IL-17A." (PMID 38164134, 2023). "Contrastingly, other studies show that anti-TNF-α medication is effective and successful for connective tissue disease (CTD), particularly SLE and cutaneous lupus erythematosus (CLE)." (PMID 37833861, 2023). "However, anti-TNFα-induced lupus is rare and systematic monitoring of autoantibodies without clinical signs should be avoided." (PMID 33802483, 2021). "Despite their therapeutic effects, these drugs block TNF, resulting in several negative side effects, including low rate of disease remission, development of fatal adverse effects such as lupus-like symptoms and lymphoma, and production of antibodies against biological TNF inhibitor." (PMID 32636750, 2020). "TNF may exert the role of inhibiting development of SLE at the early stage because of inducing apoptosis and plays the role of promoting the progress of SLE at the late stage because of activating NF‐kB in lupus mice." (PMID 32994999, 2020). "It is notable that IL‐38 injection significantly reduced the levels of inflammatory cytokines IL‐1β, TNF‐α, IL‐6 and IL‐23 in plasma, demonstrating that IL‐38 is able to protect mice from lupus development, and has a negative role in regulating inflammatory cytokines both in vitro and in vivo." (PMID 33079487, 2020). "Interestingly, TNF, IL-17, IL-1, and S100A8/S100A9 have been described to form a positive feedback network driving disease activity in murine models of auto-immune arthritis or systemic lupus erythematosus." (PMID 33643287, 2020). "The present study was the first one to confirm the hypothesis that children and adolescents with childhood-onset systemic lupus erythematosus have a less healthy nutritional status, lipid and proteomic profile, homocysteine, folate, hs-CRP and TNF-α levels when compared to healthy controls." (PMID 29316941, 2018). "There is no formal data on the number of cases of lupus or on the frequency of the use of immunosuppressant drugs, but information on the use of all kind of these medications, as well as tumor necrosis factor inhibitors, is available in the Colombian health market." (PMID 29561795, 2018). "In lupus-prone mice, TNF-α is detected in glomeruli, vascular smooth muscle cells, perivascular infiltrating cells and tubular epithelial cells, and the circulating level and intra-renal expression of TNF-α correlate with proteinuria and disease activity in animal and clinical studies." (PMID 26441980, 2015). "Interestingly, in contrast to lupus-like syndrome induced by hydralazine and procainamide, the occurrence of anti-dsDNA antibodies and hypocomplementemia is more common in anti-TNF-induced lupus, although the mechanism is not fully understood." (PMID 25216337, 2014).
lupus (continued). "Before anti-TNF therapy, no patients had clinical sign of lupus, three had positive ANA (range 1/160–1/1280), one of these (the patient with the highest level of ANA) had one time a limit positive anti-dsDNA titre (ELISA test, 46 UI; normal value <40), and nine had negative results." (PMID 15899041, 2005). "Exosomes derived from lymphocytic leukemia (CLL) can target TLR7 signaling to promote innate immunity, while exosomes isolated from systemic lupus erythematosus (SLE) patients' serum can produce abundant IFN-α, TNF-α, IL-1β, and IL-6 via the TLR1/2, TLR7, TLR9, and TLR4 pathways." (PMID 32565722, 2020). "In a pristane‐induced systemic lupus erythematosus (SLE) mouse model, pharmacological inhibition of PCSK9 significantly attenuated systemic inflammation, as evidenced by a 40–50% reduction in proinflammatory cytokines (IL‐17, TNF‐α) and increase in anti‐inflammatory TGF‐β levels (p < 0.01)." (PMID 41190281, 2025). "Many patients receiving TNF blockers develop antinuclear antibodies (ANA) or anti-dsDNA antibodies; however, most do not progress to clinical lupus." (PMID 41375587, 2025). "Certain cytokines previously associated with HRV in experimental models of acute inflammation, such as TNF-α and IL-1β, were not impacted by HRV in this study of patients with lupus." (PMID 27590046, 2016). "Administration of TNF-α to predisease NZB/W mice delayed the onset of disease, whereas administration of low, but not high, doses of TNF-α to lupus-prone mice with active disease exacerbated renal injury." (PMID 24171032, 2013). "The lack of association between disease activity and production of TNF-α by lupus monocytes is not surprising, particularly considering that although numerous reports agree that TNF-α expression is elevated in SLE, the association between TNF-α levels and disease activity is less consistent." (PMID 21423726, 2011). "Before anti-TNF therapy, no patients had clinical sign of lupus, one had positive isolated ANA (1/160) without any other lupus criteria, and no patients had anti-DNA or low complement." (PMID 15899041, 2005). "For instance, treatments commonly used in SpA, such as nonsteroidal anti-inflammatory drugs (NSAIDs) or tumor necrosis factor (TNF) inhibitors, may have variable effects or contraindications in patients with concurrent SLE due to the risk of lupus flares or drug-induced complications." (PMID 40777682, 2025). "The expressions of TNF-α and IL-6 in lupus patients are generally higher than that in healthy people, and studies have reported that the lack of IRAK1 could reduce the production of IL-6 and TNF-α." (PMID 32760274, 2020). "These mediators, as well as TNF-α, were highest in the LAUREL cohort at baseline and follow-up in those lupus relatives who remained clinically unaffected or only developed ILE and did not transition to classified SLE." (PMID 35720322, 2022).
ischemia (449 papers, 2006 to 2026). A hypoperfusion of the BLOOD through an organ or tissue caused by a PATHOLOGIC CONSTRICTION or obstruction of its BLOOD VESSELS, or an absence of BLOOD CIRCULATION. "TNF-α also attracts eosinophils, which can cause inflammation, vascular occlusion, and ischemia in the brain, similar to what is observed in skin lesions." (PMID 39882206, 2024). "For instance, TNF-α can act directly on tubular and glomerular capillaries, causing tubular necrosis and ischemia." (PMID 38686375, 2024). "On the contrary, it was shown that TNF-α increased NF-κB and improved neural viability after ischemia; NF-κB is implicated in neural development." (PMID 37676390, 2024). "In pathological conditions, increased pro-inflammatory cytokines such as IL-1β, IL6, and TNFα cause brain damage due to ischemia associated with BBB disruption." (PMID 39204239, 2024). "Previous research has shown Melittin’s anti-inflammatory actions in cases of cerebral ischemia, where it reduced the elevated cytokine levels (IL-1β, IL-6, TNF-α) post-ischemia by inhibiting the NF-κB signaling pathway linked to inflammatory factor production." (PMID 38732255, 2024). "Activation of microglia and astrocytes caused by ischemia leads to production of pro-inflammatory cytokines (IL-6, IL-1β, and TNF-α), and the release of chemotactic factors, which further increase the permeability of BBB." (PMID 38364236, 2024). "Radiation-induced thrombosis and ischemia can also cause an increase in the production of pro-inflammatory and inflammatory cytokines and chemokines, such as TNF-α, IL-1, and IL-6, which attract inflammatory cells to the wounded jaw." (PMID 37081475, 2023). "It is known that overexpression of TNF-α in normal myocardium directly causes myocardial insulin resistance, aggravating cardiac dysfunction and ventricular dilatation following ischemia." (PMID 37334749, 2023). "Conversely, TNF- α and IL-6 are associated with a tendency to develop ischemia or atherosclerotic events." (PMID 35684317, 2022). "Evidence shows that TNFα-induced necroptosis was involved in MI/R injury, myocardial TNFα level, and associated inflammatory factors were detected in MI/R (30 min ischemia/2 h reperfusion) myocardium." (PMID 35391841, 2022). "After ischemia, plasma levels of proinflammatory cytokines, such as TNF-α, IL-1, and IL-6, increase significantly and cause exacerbation of tissue damage." (PMID 38812980, 2022). "In our study, S. boulardii supplementation caused a significant suppression of TNF-α levels in serum and lung tissue in aortic ischemia-reperfusion." (PMID 33355795, 2021). "It is demonstrated that the increase of some cytokines including IL-6, IL-1β, and TNF-α in ischemia models are associated with pathways that participate in apoptotic neuronal death." (PMID 32963745, 2020). "IgG leakage, tight junction protein loss, and inflammatory cytokines IL-1β, IL-6, and TNF-α reduced in mesenchymal stem cell-treated mice compared to the control group following ischemia (p < 0.05)." (PMID 29724240, 2018). "In conclusion, flurbiprofen axetil preconditioning improves neurological function and neuronal survival after ischemia, which is associated with inhibition of IL-1β, TNF-α, and TXB2 synthesis, creating a favorable TXB2/6-keto-PGF1α ratio in rats." (PMID 29540536, 2018). "Studies that use the model of ischemia and the reperfusion, promoting acute stress, relate a rise in TNF-α to the inflammatory stimulus associated to the early tissue damage." (PMID 23401697, 2013). "Proinflammatory cytokines, such as tissue necrosis factor-α (TNF-α), interleukin (IL)-1, and IL-6, have been implicated as important mediators of ischemia/reperfusion injury following both focal and global cerebral ischemia." (PMID 23056034, 2012). "Proinflammatory cytokines, such as tissue necrosis factor-α (TNF-α), interleukin (IL)-1β, and IL-6 have been implicated as important mediators of ischemia/reperfusion injury following both focal and global cerebral ischemia." (PMID 23056034, 2012).